Y_RNA (Y RNA )
Gene: Miscellaneous RNA gene on chromosome 8 (66,653,469 to 66,653,576, forward strand). Ensembl gene ENSG00000201365.
Homologues: Orthologues: chimpanzee Y_RNA (99% identical). Paralogues in human: Y_RNA (86% identical), RNY1 (85% identical), Y_RNA (85% identical), Y_RNA (84% identical), RNY1P11 (83% identical), Y_RNA (83% identical), Y_RNA (82% identical), RNY1P12 (81% identical), Y_RNA (81% identical), RNY1P10 (81% identical), RNY1P5 (80% identical), RNY1P7 (80% identical), and 95 more.